BRAF (B-Raf proto-oncogene, serine/threonine kinase)
Diseases named in the same sentence as BRAF in open-access papers (continued):
Sharing a sentence is not in itself a finding about the gene and the disease.
colon carcinoma (continued). "We found that BRAF mutated colon cancer had more stromal cells, more immune cell infiltration, and lower tumor purity." (PMID 34381786, 2021). "Regarding genetic alterations, for NMAC, right-sided colon cancer had more BRAF mutations than left-sided colon cancer and rectal cancer." (PMID 33738258, 2021). "In the second cohort (n = 5), all colon cancers had a BRAF V600E mutation; however, again, in contrast to CMS1, all tumors were MSS and had otherwise a very low frequency of mutations (≤3 mutations in the panel)." (PMID 34885128, 2021). "BRAF mutated colon cancer often derives from sessile serrated adenoma and tends to be high grade, poorly differentiated, and located on right-sided colon, and has more mucinous component, more peritoneal and lymph node metastases, but less lung metastases." (PMID 34381786, 2021). "In the present study, we have identified immune characteristics of BRAF mutated colon cancer and have investigated the immune microenvironment of BRAF mutated colon tumors." (PMID 34381786, 2021). "Since many of these proteins including NPM1, RanBP1, eIF4E and PSPH were previously reported to be transcriptional targets of c-Myc, expression of c-Myc in colon cancer cell lines differing in their BRAF mutational status was also examined." (PMID 34201061, 2021). "MiR-320e was reported to be significantly elevated in patients with recurrent stage III colon cancer harboring the same V600E BRAF mutation, as in ECD." (PMID 33153128, 2020). "The prevalence of BRAF mutations was 16.3% (95% CI: 13.5%‐19.6%) among right‐sided colon tumors and 4.3% (95% CI: 3.4%‐5.6%) among left‐sided colon tumors (P < .0001)." (PMID 31856410, 2020). "The BRAF mutation is a novel biomarker that is gaining interest due to its association with a worse prognosis when compared to BRAF wild-type colon cancer." (PMID 32599843, 2020). "A subgroup harboring a BRAF mutation has been described, and represents approximately 10% of the patients diagnosed with colon cancer." (PMID 32545884, 2020). "This study demonstrates a strong correlation between intracellular signaling protein concentrations in colon cancer tissue and mutational BRAF status and significantly prolonged overall survival for patients with BRAF mutations and low levels of AKT or ERK." (PMID 33208845, 2020). "Prognosis of patients with colon cancer depends on several factors, such as tumor molecular status (microsatellites instability, BRAF mutations), localization (right or left side), stage at diagnosis, and density and composition of the tumor immune infiltrate." (PMID 32599843, 2020). "Between 5% and 15% of CRC have BRAF mutations, typically associated with female sex and right-sided colon cancers." (PMID 32384640, 2020). "BRAF V600E mutational analysis was carried out in 76 patients, and an association was only found in older white patients with right‐sided colon cancers, possibly indicating development via the microsatellite instability CRC pathway." (PMID 32514437, 2020). "In colon cancers in smokers of over 20 cigarettes a day, genetic disorders such as microsatellite instability, k-ras and BRAF mutations are more common." (PMID 33375262, 2020). "The poor prognosis of BRAF-V600E mutations in stage II + III colon cancer in most studies seems to be overridden by the good prognosis seen with MSI-H." (PMID 32823998, 2020). "RAS, KRAS, and BRAF mutations were found to vary significantly by tumor location, occurring more frequently among right‐sided colon tumors than left‐sided colon tumors." (PMID 31856410, 2020). "In colon cancer, the expression levels of this receptor are higher, and BRAF inhibition causes a relief of the regulatory loop, resulting in pathway rebound induced by upstream EGFR activation." (PMID 33291749, 2020). "Remarkably, nearly all BRAF-V600E tumors had low expression of Axin2, RNF43, and ZNRF3, but not vice versa, consistent with previous report of low Wnt signaling in colon tumors with MSI-H BRAF-V600E mutation." (PMID 31811196, 2019).
colon carcinoma (continued). "In colon cancer-specific DNA mutations have been identified, BRAF, K-ras, N-ras, and PIK3CA mutations." (PMID 31281432, 2019). "Overall, these genomic data clearly indicate that a subset of colon cancers, including nearly of all those with BRAF-V600E mutation, had low Wnt signaling." (PMID 31811196, 2019). "With this in mind, Sinicrope and colleagues identified two subtypes of colon cancer deficient in mismatch repair based on mismatch repair status and detection of B-Raf Proto-Oncogene (BRAF) V600E or mutations in KRAS Proto-Oncogene (KRAS)." (PMID 31390840, 2019). "In the present study, it is demonstrated that KRAS and BRAF mutations induce anoikis resistance in colon cancer (Caco-2) cells." (PMID 31545494, 2019). "In this study, we also reported the death of patient number 2 that presented the V600E BRAF mutation and a right-sided colon cancer both indicators of worse prognosis." (PMID 31344983, 2019). "Previous studies have reported that CDX2-negative colon cancer is associated with poor prognostic factors such as advanced stage, poorly differentiated cancer, vascular invasion, BRAF mutation, and CIMP positive status." (PMID 30785889, 2019). "The first was enriched in patients with BRAF mutations, right colon cancer, and advanced age, in agreement with previous findings." (PMID 31036005, 2019). "In the TCGA colon cancer cohort with 533 sequenced tumors, there are 21 tumors with G659Vfs*41 mutations and 47 tumors with BRAF-V600E mutation." (PMID 31811196, 2019). "The molecular profile of right colon cancer characterized by the presence of RAS/BRAF mutation which correlated with worse outcome." (PMID 31885734, 2019). "It is well known that aberrant activation of MAP kinase pathways induced by activating mutations in KRAS or BRAF contributes to abnormal cell growth and functions as a critical mechanism leading to tumorigenesis of colon cancer." (PMID 31409052, 2019). "A systematic review and meta-analysis of many clinical studies carried out in the last decade clearly showed that BRAF mutations in colon cancer were associated with a more than two times higher risk of mortality." (PMID 29652830, 2018). "BRAF mutation occurs in 8–15% of colon cancers (CC), and is associated with poor prognosis in metastatic disease." (PMID 29568398, 2018). "Some studies have suggested that KRAS and BRAF mutations are more frequent among colon than rectum tumors, while the chromosomal instability network is more common in rectal than in colon cancer." (PMID 29652830, 2018). "In our previous study, BRAF V600E mutations were found only in colon cancers and strongly revealed poorer OS in colon patients." (PMID 29666387, 2018). "The combination of a BRAF inhibitor with an EGFR inhibitor was recently tested in BRAF-mutated colon cancer patients with very modest therapeutic results." (PMID 29652830, 2018). "Right colon cancers showed features associated with sporadic Microsatellite Instability: predominance of female cases and BRAF mutations, and an important mucinous component." (PMID 29632645, 2018). "In colon cancer cells possessing BRAF (V600E) mutations, only simultaneous BRAF and EGFR inhibition achieved a significant inhibitory effect on tumor cells." (PMID 29652830, 2018). "The prognostic impact of KRAS mutation was recently analyzed in a large pool of colon cancer patient wild-types for the BRAF gene (to exclude from the analysis patients with mutated BRAF, who have a poor prognosis)." (PMID 29652830, 2018). "Since only one sample was detected to have a mutation in BRAF in all 34 gastric cancer samples, we only investigated the IHC characteristics in colon cancers and rectal cancers." (PMID 30416987, 2018). "In colon cancer, for example, BRAF mutations (that are relatively uncommon) are mutationally unlikely, but are strongly selected." (PMID 29748584, 2018).
colon carcinoma (continued). "The results showed that KRAS/NRAS/BRAF mutation rates in colon cancer were 44.2, 1.2, and 3.5%; in rectal cancer were 37.1, 4.3, and 0.7%; in gastric cancer were none, none and 2.9%." (PMID 30416987, 2018). "Aspirin use after colon cancer diagnosis was associated with improved overall survival in wild-type BRAF tumors, adjusted rate ratio (RR) of 0.60 (95% CI 0.44–0.83)." (PMID 28125730, 2017). "The BRAF mutation holds prognostic information in metastatic disease but its potential importance in localized colon cancer remains to be proven." (PMID 28378527, 2017). "VLX60 compromised the ubiquitin-proteasome system and was more active in BRAF mutated versus BRAF wild-type colon cancer cells." (PMID 28415818, 2017). "A random selection of 599 patients with colon cancer were analyzed, selected from the Eindhoven Cancer Registry, and BRAF and KRAS mutation status was determined." (PMID 28125730, 2017). "Vemurafenib is a potent inhibitor of the kinase domain in mutant BRAF and its use in BRAF mutated colon cancer remains to be well established." (PMID 28811946, 2017). "In resectable colon cancer patients treated with adjuvant drug therapy, the BRAF mutation has been associated with poor survival compared to wild-type BRAF." (PMID 29115941, 2017). "Patients with right colon cancer showed more mutated BRAF (39.1% vs. 5.4%), mutated PIK3CA (13% vs. 1.4%), poorly differentiated tumor (17.4% vs. 3.4%), and peritoneal involvement (26.1% vs. 8.8%) than those with left colon and rectal cancer." (PMID 29169325, 2017). "To further investigate the effects of Episilvestrol in KRAS/BRAF mutated colon cancer, we selected four more cell lines, HT29 (BRAF600E), VACO432 (BRAF600E), LOVO (KRASG13D and SW480 (KRASG12V)." (PMID 28030835, 2017). "The study opens for the potential use of analysis of RAS mutations in serum in the clinical management of colon cancer, together with a combination of BRAF mutations in serum and tumor MMR status." (PMID 28378527, 2017). "Low-dose aspirin use after colon cancer diagnosis was associated with improved survival in BRAF wild-type tumors only." (PMID 28125730, 2017). "In left-sided colon tumors, the BRAF mutation rate was 4%, which was significantly lower than right-sided colon tumors (P = 0.004)." (PMID 29156800, 2017). "Miscosatellite instability and BRAF mutation are important prognostic factors but are detected less often in rectal cancer than in colon cancer." (PMID 28865435, 2017). "Representative CIMP-H-associated features in CRC are old age, poor prognosis, female sex, a proximal colonic tumor location, poorly differentiated histology, signet ring cell histology, serrated histology, the BRAF V600E mutation, and MSI-H status." (PMID 26883113, 2016). "Nearly half of all colon cancers contain KRAS/BRAF mutations and the numbers are higher in bigger or more advanced tumors." (PMID 27351224, 2016). "In subsequent studies, we found that among wild-type KRAS colon cancer cells, those harbouring active mutations in BRAF were even more resistant to AUY922-induced apoptosis than cells with wild-type BRAF." (PMID 27391062, 2016). "Mucinous differentiation has been shown to be associated with MSI-H, CIMP-H, BRAF mutation, and proximal colonic tumor location in CRC." (PMID 26883113, 2016). "Oncogenic mutations of BRAF occur in approximately 10% of colon cancers and are associated with their resistance to clinically available therapeutic drugs and poor prognosis of the patients." (PMID 27391062, 2016). "In this report, we have presented evidence that colon cancer cells with mutations in BRAF are also resistant to HSP90 inhibitors, including AUY922 that is currently in clinical trials for the treatment of wild-type KRAS colon cancers." (PMID 27391062, 2016).
colon carcinoma (continued). "To study a potential role of mutant KRAS/BRAF in Everolimus response, we took the advantage of isogenic colon cancer cell lines with targeted disruption of WT or mutant BRAF alleles, or mutant KRAS knockin or knockout cells." (PMID 27351224, 2016). "In this study, we have examined the impact of mutations in BRAF on the response of colon cancer cells to AUY922." (PMID 27391062, 2016). "Previous studies have also revealed that SSA/Ps are significantly associated with a proximal colonic tumor location, BRAF mutations, and CIMP-H status, whereas TSAs show relatively heterogeneous clinicopathologic and molecular features." (PMID 26883113, 2016). "The BRAF V600E mutation is reportedly associated with inferior survival among colon cancer patients." (PMID 25636897, 2015). "The present study revealed that tumour dissemination is less likely to occur in colon cancer patients with microsatellite instable (MSI) disease or mutated BRAF, as compared to patients with MSS or BRAF wild-type tumours." (PMID 25884297, 2015). "R colon tumours bear more commonly BRAF mutations and the MMR phenotype, though the low incidence in our series makes them an unlikely culprit." (PMID 25970543, 2015). "Recent data on adjuvant studies in patients with stage II/III colon cancer and in metastatic disease indicate that BRAF V600E mutation is associated with worse clinical outcome." (PMID 25983749, 2015). "The present study revealed that tumour dissemination is less likely to occur in colon cancer patients displaying MSI or BRAF mutation, whereas the presence of a KRAS mutation increases the likelihood of disseminated disease." (PMID 25884297, 2015). "In this Chinese cohort of 126 sporadic colon cancer patients, we found that the BRAF V600E mutation was significantly associated with a higher metastatic rate and a poorer OS." (PMID 25367198, 2014). "Of greater interest, we found that this combination showed a synergistic antiproliferative activity and inhibition of angiogenesis in a colon cancer xenograft model with a bRAF mutation and multi drug resistant phenotype." (PMID 24495750, 2014). "Here we show that GNAS mutant colon tumors harbor recurrent KRAS or BRAF mutations, target the anatomic proximal “right-sided” colon, and exhibit a villous morphology." (PMID 24498230, 2014). "For example, a kinome-based shRNA screening study was performed to determine the mechanism of resistance against BRAF inhibitors in colon cancers that harbored an activating mutation in the BRAF oncogene." (PMID 24297677, 2014). "Taken together, these data indicate that GNAS mutant colon tumors commonly have synchronous mutations in KRAS or BRAF, are right-sided in location, and are associated with a villous morphology." (PMID 24498230, 2014). "The continuous cetuximab group had more elderly patients (age >75 years), more with a WHO performance score of 2, more with BRAF mutations, and more with primary colon cancers (vs rectal) than did the intermittent cetuximab group." (PMID 24703531, 2014). "Nevertheless, our findings suggest that prospective evaluation of the BRAF mutation status is equally important in Chinese patients with colon cancer, even though its mutation frequency (4-7%) is lower than Western patients and no effective therapy available." (PMID 25367198, 2014). "Activating mutations in both KRAS and BRAF are prevalent, and occur in high frequency in colon cancers." (PMID 24962990, 2014). "Since colon cancer cell lines used in this study harbored either different KRAS or BRAF mutation, our results suggest that B4GALNT3 knockdown suppressed cell malignant phenotype and cancer cell stemness irrelevantly to the status of KRAS and BRAF." (PMID 25003232, 2014). "The BRAF V600E mutation remained as an independent predictor for poor prognosis in patients with colon cancer (HR, 4.2; 95% CI, 1.6-11.0; P = 0.004)." (PMID 25367198, 2014).
colon carcinoma (continued). "All mutations in BRAF were from colon cancer patients and almost all were localized in the proximal colon (8/9)." (PMID 25367198, 2014). "Regarding the primary location, 64.8% of KRAS mutations (p=0.07) and 58% of PIK3CA mutations (p=0.036) occurred in left-sided colorectal tumours, whereas four (66.7%) of BRAF mutations in right-sided colon carcinomas (p=0.024)." (PMID 23374602, 2013). "Such mutated oncogenes include KRAS and BRAF that are mutually exclusive in colon tumors and are both part of the Mitogen Activated Protein Kinase (MAPK) pathway." (PMID 24244575, 2013). "Activating mutations of oncogenes such as KRAS, BRAF or PIK3CA that are common to colon cancer have been reported to be associated with resistance to cytotoxic agents or molecularly targeted drugs." (PMID 23852390, 2013). "In this study, we screened 32,171 CpG sites located at 10,537 genes in a selected cohort of 19 patients with right-sided colon cancer to obtain additional insight into the association between BRAF mutations and DNA methylation in colon cancer tumorigenesis." (PMID 23324568, 2013). "Similar results were demonstrated for BRAF mutational status in 3 colon cancer cell lines (HCT116, Colo201, and HT29), which were validated by Sanger dideoxy sequencing." (PMID 23274581, 2013). "As a novelty, we observe a strong prognostic value for relapse-free survival of the BRAF mutation status in the MSS/left-colon tumors." (PMID 24073892, 2013). "A significant increase in the BRAF mutant log2 ratios, compared with those of the BRAF wildtypes, indicates BRAF mutation-specific hypermethylation in these colon cancer samples." (PMID 23324568, 2013). "Residual colon tumor FFPE specimens with BRAF V600E or PIK3CA H1047R mutations were independently diluted in two-fold decrements." (PMID 24001039, 2013). "Subsequent studies regarding CIMP in colon cancer described a strong association between this epigenetic phenotype, BRAF mutations, and microsatellite instability (MSI)." (PMID 23324568, 2013). "The association between DNA methylation and activating BRAF mutations in colon cancer has been identified in several studies." (PMID 23324568, 2013). "The evaluation of MSI and BRAF mutation together is a useful tool for screening HNPCC in the colon cancer population." (PMID 22792460, 2012). "They did observe a significant protective effect for BRAF mutation on left side colon cancer considering other risk factors in a multifactorial analysis (HR, 0.53; P = 0.109)." (PMID 23056577, 2012). "We have already begun utilizing MSI and BRAF mutational status in a systematic way to screen for HNPCC in patients with colon cancer." (PMID 22792460, 2012). "CIMP is also associated with BRAF mutations in both microsatellite stable and unstable colon cancers." (PMID 21559209, 2011). "We examined the relationship between intake of one-carbon nutrients and alcohol and colon cancer risk, by BRAF mutation or CIMP status." (PMID 21738611, 2011). "How one-carbon nutrients affect the CpG island methylator phenotype (CIMP) or BRAF mutation status in colon cancer remains uncertain." (PMID 21738611, 2011). "Risk of colon cancer according to baseline quintiles of one-carbon nutrient intake by BRAF mutation status in tumors among 88,691 women in the Nurses' Health Study (1980–2002)." (PMID 21738611, 2011). "BRAF mutations were less frequent in colon cancer patients below 50 years relative to patients above 50 years (p-value: 0.044)." (PMID 20444249, 2010). "The locus-specific, non-BRAF associated mechanism of MLH1 methylation suggested in our study should be addressed in a larger group of early onset sporadic colon cancer patients with MLH1 methylation to provide additional insights." (PMID 20444249, 2010). "A higher frequency of CIMP-high (20/20 vs. 4/11, p = 3.1 × 10-4 (Yates' corrected)) was observed for colon cancer patients above the age of 50, concomitant with the higher number of BRAF mutations found in these patients." (PMID 20444249, 2010).